PARP1 (poly(ADP-ribose) polymerase 1)
Diseases named in the same sentence as PARP1 in open-access papers (continued):
Sharing a sentence is not in itself a finding about the gene and the disease.
breast cancer (continued). "In conclusion, PARP1 directs the transcription of some proliferation and DNA repair genes in breast cancer cells by the ADP-ribosylation of EP300, thereby causing its activation and marking nucleosomes for displacement by BRG1." (PMID 31614656, 2019). "Inhibition of BRCA1 and BRCA2 gene expression suggested a synergistic cytotoxic effect with PARP1 inhibitor based on previous findings in breast cancer with mutation of BRCA1 or BRCA2." (PMID 30719229, 2019). "It is known that high levels of PARP-1 were associated with a poor prognosis in early breast cancer." (PMID 29343717, 2018). "Poly-ADP ribose polymerase 1 (PARP1) is clinically important because of its synthetic lethality with breast cancer allele 1 and 2 mutations, which are causative for inherited breast and ovarian cancers." (PMID 30410680, 2018). "PARP1 is well-known because in its absence it exhibits synthetic lethality with breast cancer allele (BRCA)-deficient tumors." (PMID 30410680, 2018). "Despite its basic biological and clinical importance, the underlying mechanisms for the overexpression of PARP1 in breast cancer remain poorly defined." (PMID 29212245, 2017). "The critical role of PARP1 in DNA repair is manifested by its frequent upregulation in breast cancer cells, which is associated with disease progression and poor survival." (PMID 29212245, 2017). "When combining the PARP1 inhibitor olaparib with cisplatin in a BRCA1-mutated breast cancer mouse model, the combination induced a larger response than either of the two compounds alone." (PMID 27323902, 2016). "In agreement with our results, it has been reported that the expression of PARP1 is associated with the progression of various human malignant tumors, such as gastric cancer, breast cancer, ovarian cancer, glioblastoma, and chordoma." (PMID 27643881, 2016). "PARP-1 inhibitors have proven an effective monotherapy in BRCA-mutated breast cancer, ovarian cancer and prostate cancer." (PMID 27515310, 2016). "Although there are controversies, chemotherapeutic effectiveness of PARP1 inhibitors have been assessed in BRCA-deficient breast carcinomas and ovarian carcinomas with a BRCA1/2 mutation." (PMID 27643881, 2016). "Significantly, PARP1 deficiency alone induces mammary carcinoma and tumorigenesis is markedly increased when combined with other DNA damage response (DDR) genetic deficiencies." (PMID 27428646, 2016). "Inhibition of PARP-1 is a promising approach for targeted prevention of breast cancer, especially among women with deleterious BRCA mutations." (PMID 24829621, 2014). "Poly (ADP-ribose) polymerase 1 (PARP1) inhibitor (PARPi)-mediated therapy is a promising approach for familial breast cancers caused by mutations of breast cancer-associated gene-1 and -2 (BRCA1/2), yet drug resistance frequently occurs during the treatment." (PMID 24962108, 2014). "For example, breast cancer cells with mutations in BRCA1 or BRCA2 are extremely susceptible to knockdown or chemical inhibition of PARP1, which encodes poly(ADP)ribose polymerase (PARP)." (PMID 23382697, 2013). "Despite our data supports for a clear association between PARP1 and breast cancer in Saudi population and PARP1 gene plays a major role in the susceptibility to the disease." (PMID 24392019, 2013). "In the present case–control study we observed a significant association between the PARP1 Val762Ala polymorphism and the risk of breast cancer in Saudi population." (PMID 24392019, 2013). "We have also assessed the association of breast cancer risk with PARP1 SNP rs1136410 based on the estrogen receptor (ER) status of the patients." (PMID 24392019, 2013).
breast cancer (continued). "PARP1 Val762Ala also showed increased risk of breast cancer at Val/Ala allele in older age and at Ala allele in younger age, PR positive and HER2 positive patients groups." (PMID 24392019, 2013). "Distribution of genotypes and allele frequencies on PARP1 gene loci among Saudi breast cancer patients and controls." (PMID 24392019, 2013). "Aim of the following study was to analyze the genetic association of rs1136410 (Val762Ala) in PARP1 gene with the risk of breast cancer using genotypic assays and insilico structural predictions." (PMID 24392019, 2013). "The increased risk of breast cancer in subjects with the PARP-1 Ala762Ala (rs1136410) genotype is likely attributable to the reduction of PARP-1 activity." (PMID 24392019, 2013). "In this study, we found for the first time that the PARP-1 Ala762Ala (rs1136410) genotype significantly contributes to breast cancer susceptibility in Saudi population, which further extend the important role of PARP-1 in carcinogenesis." (PMID 24392019, 2013). "Our results suggest that, despite the strong biological plausibility, PARP1 is a susceptibility locus for breast cancer in Saudi population." (PMID 24392019, 2013). "To evaluate the association of PARP1 SNP rs1136410 with the age at diagnosis of breast cancer, we stratified the breast cancer cases as ≤ 48 (n = 46) and > 48 (n = 53) years of age." (PMID 24392019, 2013). "The success of the PARP-1 inhibitor olaparib in BRCA1-deficient breast cancer and the early translational work in HNSCC underpin the importance of future targeted therapy in exploiting synthetic lethality in DNA repair." (PMID 24364026, 2013). "As a result, PARP-1 inhibitors are currently being evaluated in clinical trials for their ability to enhance the efficacy of chemotherapeutic agents in ovarian and breast cancer patients that have BRCA-deficient tumors." (PMID 23254695, 2013). "In summary, our study shows for the first time a significant association between the PARP-1 Val762Ala (rs1136410) genotype and increased risk of breast carcinoma in Saudi patients." (PMID 24392019, 2013). "PARP1 is overexpressed in a variety of cancers, and its expression has been associated with overall prognosis in cancer, especially breast cancer." (PMID 22401667, 2012). "Drugs that induce DNA-strand breaks, such as cis-platinum, show increased sensitivity in pre-clinical models, and trials are now underway to study cis-platinum and PARP1 inhibitors in women with breast cancer and a BRCA mutation." (PMID 18577985, 2008). "Over the years, this knowledge has led to the use of PARP1/2 inhibitors as mainstay pharmaceutical strategies for the treatment of ovarian, pancreatic, prostate and breast cancers, holding mutations in genes encoding for proteins involved in the DNA repair mechanisms (synthetic lethality)." (PMID 39189367, 2024). "Finally, a retrospective study of patients with locally advanced breast cancer found that high levels of PARP-1 expression in pretreatment biopsies was associated with a lower lymph node stage and longer overall survival." (PMID 38675715, 2024). "Furthermore, biochemical analyses revealed that DDT26 also mildly inhibited PARP1, a critical target for treating breast cancers with BRCA1/2 mutations." (PMID 38099141, 2023). "In addition, compared to mice with a single deficiency in PARP1, a single deficiency in PARP2, or normal control mice, breast cancer mice with PARP1/2 double deficiencies have a higher percentage of CD11b+DCs in cancer tissues." (PMID 38111536, 2023). "A highly positive correlation between PARP1 expression and PARPi resistance previously has been demonstrated in breast cancer cell lines, wherein the BRCA1-mutated cell line HCC1937 had both the highest level of PARP1 expression and greatest resistance to PARPi82." (PMID 36344544, 2022).
breast cancer (continued). "Since PARP-1 inhibitors result in synthetic lethal effects, specifically in BRCA-mutated cells, MDA-MB-436 (BRCA-1-mutated breast cancer cell line) was selected to conduct a cell proliferation assay for the analogs that exhibited the most active inhibition effect against the PARP-1 enzyme." (PMID 35956876, 2022). "Although a relatively new therapeutic concept, SL strategies have already begun to enter the clinic as breast and ovarian cancers harboring BRCA1/2 (Breast Cancer Type 1/2 Susceptibility Protein) defects are now being targeted with PARP1 (Poly [ADP-Ribose] Polymerase 1) inhibitors like Olaparib." (PMID 35345853, 2022). "For example, breast cancer cells with deficiencies in HR proteins (such as BRCA1) can repair their DNA by either relying on other highly expressed HR-related proteins (such as RAD51 or PARP1) or backup DNA repair pathways such as alt-NHEJ23." (PMID 35610507, 2022). "Herein, oxadiazole based ligands that are predicted to target PARP-1 have been synthesized and screened for the loss of cell viability in mammary carcinoma cells, wherein seven compounds were observed to possess significant IC50 values in the range of 1.4 to 25 μM." (PMID 35163965, 2022). "It was shown to be upregulated in breast cancer and linked to PARP-1 inhibitors response." (PMID 33806327, 2021). "PARP1 polymorphism Val762Ala (rs1136410 T>C) may be associated with prostate cancer, esophageal squamous cell carcinoma, and breast cancer." (PMID 34150711, 2021). "In search of the underlying mechanism, we found that eIF3e deficiency causes reduced PARP1 expression and mTORC1 hyperactivation that drive breast cancer cells into senescence and secretion of inflammatory factors, providing potential novel cancer therapeutic opportunities." (PMID 33868586, 2021). "Impaired KLF4 or PARP1 has been previously linked to breast cancer formation." (PMID 33231937, 2020). "The reduction in binding to the SNV variant in in vitro binding assays was almost equal to a reduction in promotor activity in reporter gene assays, which strongly suggests that PARP-1 is a critical component for the full induction of the breast cancer-associated promoter I.3/II-region." (PMID 32059481, 2020). "However, the expression level of PARP1 has been reported to be associated with the survival of breast cancer patients, but the results are inconsistent." (PMID 32355298, 2020). "That said, whether PARP1 inhibition underlies the beneficial effects of NAM against mammary tumors remains to be experimentally verified." (PMID 32732875, 2020). "Thus, abnormal accumulation of KLF4 and PARP1 protein levels in breast cancer tissues is associated with poor prognosis." (PMID 33231937, 2020). "In breast cancer cells, PARP1 associates with active chromatin marks, CTCF, and DNase hypersensitivity sites, supporting the idea that CTCF PARylation could preferentially associate with active chromatin marks in the EBV genome." (PMID 29976663, 2018). "The PARP-1 gene polymorphisms have been previously reported to be associated with risk in various carcinomas, including colon, lung cancer, bladder, prostate, head and neck, and breast cancer." (PMID 27746584, 2016). "Taken together, this the first study that confirmed Val762Ala variant has functional effect and structural impact on the PARP1 and may play an important role in breast cancer progression in Saudi population." (PMID 24392019, 2013). "In breast cancer, PARP-1 up-regulation has been associated with decreased survival and triple-negative (TN) cancers (breast tumours in which estrogen receptor [ER], progesterone receptor [PR] and human epidermal growth factor receptor 2 [HER2] are not expressed)." (PMID 24191908, 2013).
breast cancer (continued). "Genotype Frequencies of PARP1 Gene Polymorphism in Breast Cancer Cases below 48 and above 48 years." (PMID 24392019, 2013). "Our findings suggest that PARP-1 Val762Ala variant may play an important role in the development of breast carcinoma." (PMID 24392019, 2013). "This kind of therapy could ideally selectively kill tumor cells while sparing normal cells and reduce potential off-target side effects, for example, the clinically-used poly(ADP-ribose) polymerase 1 (PARP1) inhibitors in the selective treatment of breast cancer 1/2 (BRCA1/2) deficient cancers." (PMID 35657956, 2022). "Importantly, expression of p-Y907 PARP1 is positively associated with expression of c-MET in the tumor tissues of breast cancer patients, and combination of c-MET and PARPi synergistically suppresses the growth of xenograft tumors which have high c-MET and p-Y907 PARP expression." (PMID 36284291, 2022). "Hence we speculated that PARP1 is a transcriptional regulator of CCL2 in breast cancer cells and focused on interpreting the underlying mechanisms of CCL2 regulation." (PMID 32455851, 2020). "In addition, promoter hypermethylation of PARP1, which might be associated with lower expression level of PARP1, predisposed females to breast cancer." (PMID 33112558, 2020). "The combined effect of PARP1 polymorphism Val762Ala with other polymorphism have already be reported in different cancer such as lung cancer, noncardia gastric cancer, esophageal squamous cell carcinoma, skin cancer, breast cancer, colorectal cancer and cancer." (PMID 30183716, 2018). "However, the molecular mechanism underlying the regulation of PARP1 protein levels in breast cancer remains largely unknown." (PMID 29212245, 2017). "Using Palbociclib as a reference compound, we evaluated proliferation, viability/apoptosis, cytoskeleton organization, and differential processing of the resistance-associated marker PARP1 in MCF-7 and T47D breast cancer cells." (PMID 41827879, 2026). "An analysis of the GSE28784 dataset revealed an up-regulation of PARP1 expression in docetaxel-resistant breast cancer tissues." (PMID 40927753, 2025). "We studied in vitro activity of four PARPi in Ets‐1‐expressing MDA‐MB‐231 and Ets‐1‐non‐expressing MCF‐7 breast cancer cell lines and we demonstrated that PARP‐1 inhibition increases oxidative DNA damage and oxidative stress only in MDA‐MB‐231." (PMID 39778077, 2025). "NAT10 directly interacts with PARP1, promoting the acetylation of PARP1 transcripts, conferring resistance to platinum‐based drugs, regulating the breast cancer EMT process, and promoting doxorubicin resistance." (PMID 39764566, 2025). "The combination inhibited PARP1 activity in the chromatin, resulting in deregulation of recombination pathway in breast cancer cells." (PMID 40502812, 2025). "This preliminary study supports the effectiveness of PARPi in Ets‐1‐expressing breast cancer cells and reveals the possible mechanism of oxidative DNA damage induction through PARP‐1 inhibition." (PMID 39778077, 2025). "Due to its role in DNA repair, PARP‐1 expression is increased in several types of cancers (e.g., breast cancers) that have high levels of DNA damage, promoting thus tumor progression." (PMID 39778077, 2025). "In acute myeloid leukemia and breast cancer cells 46, low doses of DNMTis in combination with PARPis have been shown to increase the retention of PARP1 on chromatin through the induction of PARP1-DNA adducts and the covalent binding of DNMTs." (PMID 40520005, 2025). "The present study reports the possible mechanism through which PARP‐1 inhibition induces death of MDA‐MB‐231 breast cancer cells line." (PMID 39778077, 2025).
breast cancer (continued). "The mechanism of the antitumor effect of PARP‐1 inhibition was investigated in the Ets‐1‐expressing MDA‐MB‐231 breast cancer cells." (PMID 39778077, 2025). "In breast cancer, research has been largely limited to analyzing the expression status and clinical significance of the PARP1 gene." (PMID 40564403, 2025). "In this study, we found that the enzymatic activity of PARP1 is dispensable for the survival of a BRCA1 mutant (BRCA1m) breast cancer model." (PMID 41459749, 2025). "DHC-1, a potent and selective PARP1 inhibitor, selectively inhibited PARP1 activity and showed efficacy in BRCA1-deficient breast cancer and BRCA2-deficient pancreatic cancer cell lines." (PMID 40521389, 2025). "Given the widespread clinical use of PARP1 inhibitors for treating BRCA-mutant breast cancers, understanding the role of parthanatos is crucial." (PMID 40564403, 2025). "This review comprehensively discusses the recent advances in computational chemistry for the discovery of PARP1 inhibitors, focusing on their application in breast cancer therapy." (PMID 41304924, 2025). "In mutant BRCA1/2 breast cancers, PARP1’s activity becomes crucial on the basis of defective homologous recombination repair (HRR), creating a synthetic lethal dependence exploited by inhibitors." (PMID 41304924, 2025). "In an earlier study, we found that ADPr PARP1 levels were highest in untreated MDAMB436 cells compared to the other breast cancer cell lines, suggesting increased PARP1-mediated DNA damage repair activity." (PMID 40669753, 2025). "We suggest that the inhibition of PARP‐1, which it is known to induce Ets‐1 accumulation, increases oxidative DNA damage only in breast cancer cells expressing Ets‐1." (PMID 39778077, 2025). "Researchers have targeted gene combinations such as BRCA1 and BRCA2, frequently found mutated in breast and ovarian cancer, and PARP1 and BRCA1, commonly mutated in breast cancer." (PMID 38195537, 2024). "Given that overexpression of Poly (ADP-ribose) polymerase-1 (PARP1) and Neuropilin-1 (NRP1) is implicated in the pathogenesis of human breast cancer, the design of dual PARP1/NRP1 inhibitors has wide therapeutic prospect." (PMID 39679370, 2024). "The DNA repair protein PARP-1 emerged as a valuable target in the treatment of tumor entities with deficiencies of BRCA1/2, such as breast cancer." (PMID 39456536, 2024). "BRG1 complexes formed at these sites interact with EP300 and PARP1 to guide breast cancer cell proliferation and transcription of DNA repair genes." (PMID 38365747, 2024). "One report showed PARP-1 mediated positive regulation of ribosomal biogenesis in breast cancer cells, but nucleolar proteins or nucleolar architectures were not discussed." (PMID 39294821, 2024). "Other potential PARP1-targeting tracers have been tested in preclinical models carrying breast cancer." (PMID 39768978, 2024). "In the current study, we investigated the molecular consequences of XRN2 deficiency in lung and breast cancer cells in conjunction with PARP inhibition via Rucaparib and Olaparib to gain mechanistic insights into the synthetic lethality of XRN2 and PARP1." (PMID 38339346, 2024). "The combination of c-Met and PARP1 inhibitors synergistically suppressed breast cancer cell growth in vitro and in xenograft tumor models." (PMID 39001541, 2024). "PARP1 inhibitors have been reported and used for breast cancer therapy in recent years, especially in TNBC." (PMID 38561176, 2024). "Given the important role of PARP1 in human breast cancer and the issue of drug resistance to PARP1 inhibitors, the development of novel and efficient anticancer agents is an important way to prevent cancer proliferation and migration." (PMID 39679370, 2024). "Recent studies have accentuated the potential benefits of combining NAMPT inhibitors and PARP1 inhibitors to enhance therapeutic outcomes, particularly in breast cancer." (PMID 38930900, 2024).